PDCD1 (programmed cell death 1)
Diseases named in the same sentence as PDCD1 in open-access papers (continued):
Sharing a sentence is not in itself a finding about the gene and the disease.
tumor (continued). "This has been attributed to a number of factors: a low rate of tumor mutational burden, generally inadequate T cell infiltration, and relatively low expression of immune regulation markers, including programmed cell death 1 (PDCD1) and its ligands (PD-L1 and PD-L2)." (PMID 36301668, 2022). "Immune checkpoint inhibitors (ICIs) reduce immunosuppression in the tumor microenvironment and reactivate the anti-tumor function of T cells by inhibiting cytotoxic T lymphocyte-associated protein 4 and programmed cell death-1 pathway/programmed cell death receptor ligand-1 (PD-L1)." (PMID 36386191, 2022). "The evasion of tumor cells from immunorecognition was associated with elevated expression of immune checkpoint molecules such as programmed cell death-1 (PD-1, CD279), its ligand PD-L1 (CD274), cytotoxic T-lymphocyte associated protein-4 (CTLA-4, CD152), or the cell surface molecule B7-H3 (CD276)." (PMID 35628262, 2022). "While, CMS1 tumors exhibit potent anti-tumor activity, transcription of genes encoding ICs such as PDCD1, CD274, CTLA4, and LAG3 may aid tumor immune escape in these tumors." (PMID 33477864, 2021). "High levels of tumor-infiltrating lymphocytes, increased expression of programmed cell death-1 (PD-1), and a high tumor mutational burden suggests that immunotherapy may be a viable treatment strategy." (PMID 34638817, 2021). "Immune checkpoint inhibitors (ICIs), by targeting cytotoxic-T-lymphocyte-associated protein 4 (CTLA-4), programmed cell death 1 (PD-1), or PD-ligand 1 (PD-L1), have yielded durable anti-tumor responses and long-term remissions in non–small cell lung cancer (NSCLC) and other cancer types." (PMID 35186013, 2021). "MDSCs inhibit NK-cell-mediated ADCC by repressing the Fc receptor on the surface of NK cells and secrete TGF-β1 to inhibit adaptive immune responses via effector T-cell function, causing expression of Programmed cell Death-1 (PD-1) on the surface of Tumor-Infiltrating Lymphocytes (TILs)." (PMID 34830776, 2021). "We next examined whether PDCD1 polymorphisms affected mRNA expression in tumour biopsies and PBMCs from HCC patients." (PMID 32937024, 2021). "In agreement with our flow cytometry results, we identified a significant upregulation in several genes encoding for immune checkpoint inhibitory molecules (e.g. Pdcd1, Lag3, Ctla4, Icos, Tigit, Tnfrsf18) in tumor-infiltrating CD4/ALK4-KO CD4+ T cells, compared to WT CD4+ T cells." (PMID 34548096, 2021). "Immunotherapy and modulation of the tumor microenvironment are rapidly developing fields of interest in gynecologic oncology translational research; examples include the PD-1 (programmed cell death 1) and CTLA-4 (cytotoxic T-lymphocyte-associated protein 4) axes and the Wnt pathway." (PMID 33918476, 2021). "Upon activation, we observed altered transcription of KITLG, TGFB1, IFNG, SPP1, IL17A and PDCD1, whose associated functions and expression pattern marked and improved OS of BrC patients, supporting that MCs contribute with a tumor stroma with anti-tumoral functions in BrC." (PMID 32722549, 2020). "Among TILs, we noted that ~87% of GP66-specific CD4+ T cells expressed programmed cell death 1 (PD-1), encoded by Pdcd1 and a marker of antigenic stimulation, suggesting that it could serve as an indicator of tumor specificity." (PMID 31801070, 2019). "In addition, tumor cells activate immune checkpoints by promoting the binding of programmed cell death ligand 1 (PD-L1) to programmed cell death 1 (PD-1) on T lymphocytes, which inhibits the antitumor immune function of cytotoxic T lymphocytes and causes immune escape of tumor cells." (PMID 37900137, 2023). "In addition, eTregs express immune checkpoint molecules, such as cytotoxic T-lymphocyte-associated protein 4 (CTLA-4) and programmed cell death-1 (PD-1), suggesting that controlling tumor-infiltrating Tregs may be a potential target for cancer immunotherapy." (PMID 35438346, 2022).
tumor (continued). "The rs7603052 polymorphism in PDCD1 and rs17718883 in CD274 were significantly associated (p = 0.033 and p = 0.043 respectively) with PD-L1 expression in tumor-infiltrating immune cells (TIICs)." (PMID 42074079, 2026). "Together, these data support that Pdcd1 expression in migratory DCs exhibits an immunosuppressive gene signature which has been recently described in myeloid cells, including DCs, in tumor microenvironments." (PMID 41542406, 2026). "Inversely, eliminating PD-1 in Pdcd1 KO, APCs exhibit an increased ability to activate T-cells in a tumor model, resulting in better tumor control." (PMID 41542406, 2026). "For example, Lactobacillus rhamnosus GG increased the numbers of tumor-infiltrating dendritic cells (DCs) and T lymphocytes, which improved the anti-tumor effectiveness of anti-programmed cell death 1 (PD-1) immunotherapy." (PMID 40693815, 2025). "The efficacy was further enhanced by TGFBR2 and PDCD1 knockout, which helped overcome the immunosuppressive tumor microenvironment." (PMID 41374990, 2025). "For instance, upregulated PD-L1 on tumor cells typically engages with programmed cell death 1 (PD-1) on effector T (Teff) cells, leading to a reduction in effector cytokine secretion and inducing apoptosis of Teff cells." (PMID 39776799, 2025). "The mutation rate for PDCD1 was 17%, and for LAG3 it was 17% and 13%, respectively, in both tumor types." (PMID 40076932, 2025). "Further exploration of tumor‐associated immune checkpoints and the risk model is underway, revealing the high expression of TIGIT, PDCD1, and PDCD1LG2 in the low‐risk group." (PMID 38546286, 2025). "Specifically, butyrate depletion in tumor-adjacent niches leads to HDAC-mediated hyperacetylation of the PDCD1 promoter, which is then recognized and bound by ELF3 and ATF4." (PMID 41438381, 2025). "Programmed cell death protein 1 (PDCD1) is an immunosuppressive receptor expressed on activated T-cells whose ligand is on tumor cells, such as CLL cells." (PMID 41249728, 2025). "Stage-specific analysis showed increasing PDCD1 expression with advancing tumor stages, suggesting its role as a dynamic immunological biomarker." (PMID 40927719, 2025). "NOX‐A12 displays a synergistic action with programmed cell death 1 (PD‐1) blockade by enhancing T‐cell infiltration in heterotypic tumour‐stroma spheroids." (PMID 39855896, 2025). "The expression levels of immune checkpoints, including BTLA, VTCN1, CD276, PDCD1, CD160, NRP2, and CD200, as well as the tumor-associated fibroblast marker FAP, were found to be higher in the high-risk group." (PMID 40364849, 2025). "Immune-targeted therapies break the cancer immune tolerance, restoring T-cell recognition against tumor cells and restraining the cytotoxic T-lymphocyte-associated antigen 4 (CTLA-4) and the programmed cell death 1 (PD-1)/ligand 1 (PD-L1) pathways." (PMID 40227797, 2025). "These therapies are monoclonal antibodies which target cytotoxic T-lymphocyte antigen 4 (CTLA-4), programmed cell death 1 (PD-1), or programmed cell death ligand 1 (PD-L1) and reduce tumor-induced T-cell suppression." (PMID 40881866, 2025). "For instance, pembrolizumab inhibits the T-cell pathway, and because T-cell function is compromised in CLL patients, cells in the tumor microenvironment express the PDCD1 gene more frequently." (PMID 41249728, 2025). "Genetic SPP1 deficiency in macrophages delays hypoxic adaptive tumor growth and enhances the tumor response to anti-programmed cell death-1 (anti-PD-1) therapy." (PMID 41425545, 2025). "Immune checkpoint genes (e.g., PDCD1 and CTLA4) are often closely associated with immune escape mechanisms, as tumor cells express immune checkpoint molecules to suppress immune system attacks, thereby evading host immune surveillance." (PMID 40331946, 2025). "Fourth, PIEZO1 shows positive associations with tumor microenvironment scores (Stromal/Immune/ESTIMATE) and immune checkpoint markers (CD274, CTLA4, LAG3, PDCD1, PDCD1LG2)." (PMID 40977743, 2025).
tumor (continued). "Once the subcutaneous tumor volume reached 100 mm3, the mice were randomly divided into four treatment groups: IC+si-nc+IgG, IC+si-circGRAMD4+IgG, IC+si-nc+anti-PDCD1, and IC+si-circGRAMD4+anti-PDCD1." (PMID 40373256, 2025). "The association between PIEZO1 and tumor microenvironment scores (Stromal, Immune, ESTIMATE) or immune checkpoint markers (CD274, CTLA4, LAG3, PDCD1, PDCD1LG2) were analyzed using the R language." (PMID 40977743, 2025). "The interaction between programmed death ligand 1 (PD-L1; also called CD274 or B7-H1) on tumor cells and programmed cell death 1 (PD-1) on activated T cells regulates immune evasion, leading to T cell exhaustion." (PMID 40779629, 2025). "Programmed cell death 1 (PD-1) and programmed cell death ligand (PD-L1) are critical immune checkpoint molecules involved in maintaining immune tolerance, but tumor cells exploit this pathway to evade detection by the immune system." (PMID 40313949, 2025). "The immune response activates tumor immune resistance, characterized by the upregulation of anti-programmed cell death 1 (PD-1) and anti-programmed cell death ligand 1 (PD-L1)." (PMID 40022109, 2025). "Knockout of the Programmed Cell Death Protein 1 (PDCD-1) gene can help keep anti-tumor activity strong and avoid immune suppression and T cell exhaustion." (PMID 41476860, 2025). "Tumour-infiltrating lymphocytes (TILs) exhibit elevated expression of exhaustion markers such as PDCD1, LAG3, and HAVCR2, accompanied by reduced effector cytokines, reflecting chronic antigen exposure." (PMID 41179304, 2025). "Despite the challenges posed by the immunosuppressive tumor microenvironment, therapies such as programmed cell death 1 (PD-1) checkpoint inhibitors and chimeric antigen receptor-T (CAR-T) cells are under investigation." (PMID 40527837, 2025). "ICB targeting programmed cell death-1 (PD-1), its ligand (PD-L1), or cytotoxic T-lymphocyte-associated antigen 4 (CTLA-4) has shown durable anti-tumor effects in various cancers." (PMID 40519901, 2025). "CD96, CTLA-4, and PDCD-1 are important immune checkpoint proteins that play a crucial role in tumor immune evasion." (PMID 40746529, 2025). "The emergence of immune checkpoint blockade (ICB) therapy, especially targeting programmed cell death 1 (PD-1) and its ligand PD-L1, has revolutionized tumor treatment, paving the way for the era of immunotherapy." (PMID 39941891, 2025). "Our analysis has revealed a positive correlation between ETS1 and the immune checkpoints PDCD1 and TIGIT, which are linked to immune dysfunction and tumour progression." (PMID 41162582, 2025). "A hallmark of T cell exhaustion is the sustained expression of markers such as Tox, Ctla4, Entpd1, Pdcd1, and Havcr2, many of which were enriched in the tumor-infiltrating subset (Cluster 5)." (PMID 40229241, 2025). "In SKCM, however, the expression of PDCD1 is significantly higher in tumor samples than in normal samples (p < 0.05), as indicated by the red asterisk." (PMID 40149458, 2025). "In murine tumor models, preliminary evidence indicates that chronic stress can impair the response to programmed cell death-1 (PD-1)/PD-L1 blockade." (PMID 38740994, 2024). "Cancer develops as tumor cells create subclones and strive to avoid immune surveillance via immune-silencing strategies such as the Programmed Cell Death 1 (PD1)/Programmed Cell Death 1 Ligand 1 (PDL1) blockade." (PMID 39336806, 2024). "In line with this view, there was a higher PDCD1 expression in peri-tumor samples compared with CVH." (PMID 39944754, 2024). "CD274 is predominantly expressed by tumor cells, binding with programmed cell death-1(PD-1) on the surface of T cells and triggering immune escape." (PMID 38233752, 2024). "Research has demonstrated that c-CBL possesses the ability to change the tumor microenvironment and impede the activity of the programmed cell death-1 (PD-1) protein." (PMID 39130630, 2024).
tumor (continued). "Many laboratories also report the tumour mutation burden (TMB) score that is associated with immune cell infiltration and increased sensitivity to programmed cell death-1 (PD-1) or PD-1 ligand (PD-L1) blockade." (PMID 38287327, 2024). "Therapy with immune checkpoint inhibitors (ICIs) such as targeting programmed cell death 1 (PD-1) and programmed cell death ligand 1 (PD-L1) has been proven to be effective anti-tumor agents in HCC." (PMID 38690276, 2024). "Programmed cell death 1 (PD-1) and programmed death-ligand 1 (PD-L1), the most studied immune checkpoints, play essential roles in tumor progression." (PMID 38426097, 2024). "For example, CRISPR/Cas9-mediated knockout of programmed cell death 1 (PD-1) in mouse models is a prevalent method to enhance anti-tumor responses and reduce CAR-T cell exhaustion." (PMID 39538305, 2024). "Programmed Death Ligand 1 (PDL1) helps the tumor cells to escape the immune system detection by binding to the Programmed Cell Death 1 (PD1), a cell death receptor expressed on T lymphocytes." (PMID 39669309, 2024). "Immune checkpoint inhibitors (ICIs) have dramatically updated tumor therapeutic regimens, including therapies targeting programmed cell death 1 (PD-1), programmed cell death-ligand 1 (PD-L1), and cytotoxic T-lymphocyte antigen 4 (CTLA-4)." (PMID 38373990, 2024). "Programmed cell death 1 (PD-L1) is an important immunosuppressive molecule that promotes tumor growth by inhibiting the activation of T cells." (PMID 38403820, 2024). "In an immunosuppressive process, programmed cell death ligand 1 (PD-L1) in tumor cells binds to programmed cell death-1 (PD-1) in CTLs, preventing their attack." (PMID 38473345, 2024). "The biomarker data show that cibisatamab treatment triggered the relocalization of CD8 T cells from the periphery and/or the expansion of pre-existing CD8 T cells within the tumour, as well as increased PDCD1 levels, leading to an inflamed tumour phenotype." (PMID 38750034, 2024). "As an inhibitor of the host immune response, PD-L1 induces apoptosis and/or inhibition of tumor-specific T cell activation and proliferation, cytolytic function, and cytokine production, mostly by binding to programmed cell death-1 (PD-1) receptor." (PMID 38673455, 2024). "A recent study has also shown that tumor cells can express PDCD1, potentially aiding in immune evasion and enhancing invasive capabilities." (PMID 39640266, 2024). "Since most patients with advanced lung cancer lose the opportunity for surgical resection, they often require anti-tumor immunotherapy, such as anti-programmed cell death-1 (PD-1) immunotherapy." (PMID 39211047, 2024). "Immune checkpoint inhibitors (ICIs) are a class of drugs targeting programmed cell death 1 (PD-1) and programmed death-ligand 1 (PD-L1), thus regulating the immune checkpoints and enhancing the function of the immune system for tumor suppression." (PMID 38612563, 2024). "These 2 cell clusters were also co-expressing with activation markers (Pdcd1 and Ctla-4) and effector molecule (Gzmb an Ifng), suggesting the strong proliferative and anti-tumor activity." (PMID 38280084, 2024). "It enhances malignant tumor immune escape by binding to programmed cell death-1 (PD-1) receptors on immune cells." (PMID 38762481, 2024). "Our results confirm that most immune checkpoints (such as CTLA-4 and PDCD1) in the C3 subtype (βAMRGs-active) exhibit low expression levels, implying an augmented anti-tumor immune response." (PMID 38637116, 2024). "By HCC development, it is likely that tumor-driven immune suppression and T cell exhaustion contribute to a further increase in PDCD1 expression, making its upregulation more pronounced in this specific context." (PMID 39944754, 2024). "These included a major Prf1highGzmhighPdcd1+Havcr2+ cluster resembling “exhausted” T (TEX) cells and a Pdcd1+Tcf7+Slamf6+ cluster resembling “stem-like” T cells, that were predominantly tumour-resident and expanded with anti-PD-L1." (PMID 38267413, 2024).
tumor (continued). "Of note, several negative regulators of anti-tumor responses were down-regulated in CUL5 KO cells including exhaustion-associated biomarkers (NR4A2, PDCD1 and CD160), myeloid-derived suppressive cell promoting cytokine CSF2, and pro-apoptosis factor BCL2L11." (PMID 38242867, 2024). "A hallmark of T cells exhaustion is persistent expression of markers including Tox, Ctla4, Entpd1, Pdcd1, Havcr2, and others, many of which were expressed in the tumor TEX subset." (PMID 38496632, 2024). "One prominent example is the receptor programmed cell death 1 (PD-1) and its ligand (PD-L1), which is a key inhibitor of anticancer T-cell responses in the tumor microenvironment." (PMID 38467935, 2024). "We found that CD274 was mainly expressed in tumor cells, whereas the expression of PDCD1 in the immune cells in the low-DR group was higher than that of those in the high-DR group." (PMID 38507875, 2024). "So, by inhibiting the RTK pathway, the mediation of cellular proliferation is reduced.Dysregulation of cell proliferation is a key feature of cancer, and we can label PDCD1 as a tumor-promoting gene." (PMID 39064019, 2024). "Checkpoint inhibitors targeting the programmed cell death-1 (PD-1) protein and its ligand (PD-L1), known as the PDx axis, have successfully achieved responses in a number of tumor types, including hematopoietic malignancies." (PMID 39456538, 2024). "Increased PDE7B expression leads to the inhibition of PDCD1 expression, triggering immune suppression and restraining the invasion and migration abilities of tumor cells." (PMID 39640266, 2024). "To date, the programmed cell death-1 (PD-1)/programmed cell death ligand-1 (PD-L1) signaling pathway has been the most extensively studied pathway in tumor immunotherapy." (PMID 38312843, 2024). "LGALS3 expression showed a significant positive association with CD274, TIGIT, PDCD1, HAVCR2, CTLA4, LAG3, as well as PDCD1LG2 after adjustment for tumor purity in HCC." (PMID 38643145, 2024). "Third, the correlation module results showed that DSN1 was related to some well-known tumor immune-related biomarkers, such as PDCD1, CD274, PDCD1LG2, and CTLA4." (PMID 39555702, 2024). "The nanomedicine significantly improved the efficacy of programmed cell death 1 (PD‐1) immune checkpoint blockade therapy and achieved continuous tumor elimination." (PMID 38063781, 2024). "The combination of CXCR2 inhibitors with anti-PD1 (programmed cell death 1) treatments shows potential in transforming pro-tumour TANs into anti-tumour counterparts." (PMID 39320855, 2024). "This analysis showed that the presence of UPP1high tumor cells was significantly positively associated with FOXP3+ regulatory T cells (Tregs), MMP11+ cancer-associated fibroblasts (CAFs), LAG3 + PDCD1 + CD8+ exhausted T cells, and M2-like SPP1+ macrophages." (PMID 38331898, 2024). "The programmed cell death-1 (PD-1)/ programmed cell death ligand-1 (PD-L1) pathway represents an adaptive immune resistance mechanism exerted by tumor cells in response to endogenous immune anti-tumor activity." (PMID 37964265, 2023). "Oral administration of live Lactobacillus rhamnosus GG has also been found to increase tumor-infiltrating DCs and T cells and further augment the antitumor activity of anti-programmed cell death 1 immunotherapy." (PMID 37447263, 2023). "We further analyzed the tumor microenvironment between different RiskScore groups, and it was also apparent that the expression of PDCD1, CD274, CTLA-4, HAVCR2 and LAG3 in the low-RiskScore group was relatively high." (PMID 37154982, 2023). "Programmed cell death 1 (PD-1) signaling pathway plays an crucial role in immune regulation of tumor and autoimmune diseases." (PMID 37292207, 2023). "Recently, immunotherapy has fundamentally altered the direction of tumor treatment; PDCD1/PDCD1 ligand 1 (PDCD1LG1) drugs have been applied in first-line clinical trials for GAC." (PMID 37874419, 2023).